NSUN3 (NOP2/Sun RNA methyltransferase 3)
Diseases named in the same sentence as NSUN3 in open-access papers (continued):
Sharing a sentence is not in itself a finding about the gene and the disease.
tumor (continued). "Thus, our data show that the transcriptional profile of NSUN3-depleted tumours is driven by mitochondrial activity, and that hypomodified mitochondrial tRNAMet metabolically reprograms primary tumours." (PMID 35768510, 2022). "On the contrary, in lung squamous carcinoma, while most of the m5C-regulators showed significantly different expression between tumor and normal samples, only NSUN3 could significantly predict prognosis (and NSUN4 almost significantly)." (PMID 36060802, 2022). "To study whether repression of mitochondrial translation affected tumour cell invasion similarly to depletion or inhibition of NSUN3, we exposed OSCC tumoroids to the antibiotics and measured their invasive capacity." (PMID 35768510, 2022). "The levels of NSUN3 protein expression were comparable in primary tumours and lymph node metastases, which corroborates our finding that orthotopically transplanted tumours and their matching lymph node metastasis also had similar proportions of CD36HCD44H cells." (PMID 35768510, 2022). "We identified a set of 1,708 transcripts that were commonly deregulated in NSUN3-depleted tumours." (PMID 35768510, 2022). "In this study, we used the TISCH and TIMER databases to analyze the correlation between m5A regulators in LUSC and the six major immune cells in the tumor immune microenvironment, and found that NSUN3 and NSUN4 were expressed to a certain extent in immune cells." (PMID 34195072, 2021). "Therefore, we sought to exclude that other unknown functions of NSUN3 contributed to tumour cell invasion and metastasis." (PMID 35768510, 2022). "B19 binds specifically to NSUN3, activates the AMPK/STAR3 signaling pathway, inhibits STAR3 phosphorylation, disrupts mitochondrial energy metabolism, and suppresses tumor proliferation." (PMID 41413017, 2025). "The discovery that NSUN3 is involved in the regulation of tumor immunity in NSCLC, and provides ideas for the subsequent anti-tumor target drug design and the development of new tumor immunotherapy strategies." (PMID 40279954, 2025). "Next, we further explored the expression of NSUN3 in TCGA-LIHC and found that it was significantly elevated in tumor tissues." (PMID 37114236, 2023). "In contrast, the expressions of NSUN3, NSUN4, NSUN7, TRDMT1, DNMT1, YBX1, and TET2 were low in tumors and had a tumor-suppressive effect." (PMID 36661693, 2022). "Compared with the adjacent mucosa, the expression of NSUN3 (p < 0.001) and TET2 (p < 0.001) in the tumor group was significantly downregulated." (PMID 35281843, 2022). "The expressions of DVL1, MRPL4, and NSUN3 were relatively higher, while that of RPH3A was relatively lower in the tumor tissues." (PMID 36035311, 2022). "For clinicopathological parameters, consistent with previous result, the level of NSUN3 and NSUN6 was increased in tumor samples versus normal samples." (PMID 33365328, 2020). "The level of NSUN3 and NSUN6 was increased in tumor samples, whereas the level of ALYREF, NSUN5, and NSUN7 was decreased in tumor samples." (PMID 33365328, 2020). "Furthermore, NSUN3 depletion enhanced CD8+ T-cell-mediated cytotoxicity against NSCLC cells and suppressed tumor growth in vivo." (PMID 40279954, 2025). "Elevated NSUN3 expression catalyzes m5C modification at mitochondrial tRNA-C34, increasing m5C and f5C levels, which enhances mitochondrial translation, supports OXPHOS, and promotes cancer cell invasion and metastasis from the primary tumor." (PMID 41413017, 2025). "NSUN3 and NSUN2 expressions are consistently upregulated in various tumour samples." (PMID 38943267, 2024). "Similar to our findings in 2D-cultured cells and tumours formed in vivo, the spheres also switched to glycolysis in the absence of NSUN3, as shown by enhanced uptake of glucose." (PMID 35768510, 2022). "Metastases into both the lymph nodes and lungs were consistently decreased in tumours that lacked a functional NSUN3 protein." (PMID 35768510, 2022).
tumor (continued). "To identify mitochondria-driven gene expression signatures that correlated with metastasis, we transcriptionally profiled the primary tumours expressing or lacking NSUN3." (PMID 35768510, 2022). "Moreover, five writers (NOP2, NSUN2, NSUN3, NSUN4 and NSUN5), one reader (ALYREF) and two erasers (TET2 and TET3) were consistently upregulated in UCB tumor tissues compared to adjacent normal tissues from TCGA cohort (fold change > 1.1, P-value <0.05, occurrence rate > 50%)." (PMID 36806253, 2023).
cancer (16 papers, 2019 to 2025). A tumor composed of atypical neoplastic, often pleomorphic cells that invade other tissues. "NSUN3-mediated mt-tRNA m5C modification is closely associated with cancer cell metastasis, and a recent study reported that when cancer cells plan to invade and spread, their mitochondrial tRNAs are modified with m5C, thus promoting cancer cell metastasis." (PMID 39019857, 2024). "Consequently, maximal cellular respiration was reduced when mt-tRNAMet was hypomodified, and the basal extracellular acidification rate (ECAR) was higher overall in NSUN3-deficient cancer cells." (PMID 35768510, 2022). "We discovered that FAM110B expression often showed a favorable correlation with pan-cancer gene expression associated with m1A, m5C, and m6A, particularly in YTHDF3, YTHDC1, NSUN3, TET2, and METTL14." (PMID 39170745, 2024). "When the expression of NSUN3 was turned off, m5C modification of mitochondrial tRNA was also reduced, which was accompanied by a significant decrease in cancer cell invasiveness." (PMID 39019857, 2024). "In contrast, NSUN3-mediated mitochondrial tRNA m5C modification is a major factor in cancer cell metastasis." (PMID 39019857, 2024). "A concerning overexpression is that of the NSUN3 gene, as it has been involved in the promotion of cancer cell invasion and metastasis by favoring the synthesis of proteins participating in the mitochondrial respiratory chain." (PMID 37894381, 2023). "Although the RNA levels of both enzymes increased in cancer cells, the expression of NSUN3 was more variable." (PMID 35768510, 2022). "Mitochondrial translation is disrupted after gene knockout in NSUN4-deficient mice, and research on NSUN3 and NSUN4 in cancer is limited." (PMID 34195072, 2021). "NSUN3 is closely related to mitochondrial diseases and cancer." (PMID 41462962, 2025). "It has been reported that NSUN3-mediated m5C modification of mitochondrial tRNA enhances energy supply by promoting protein synthesis in the mitochondrial respiratory chain, thereby promoting cancer cell invasion and metastasis." (PMID 37114236, 2023). "Regarding NSUN3, considering its function as mtRNA modifier, and the metabolic flexibility and plasticity during cancer progression, NSUN3 could play a role in the metabolic adaptability required for metastasis formation." (PMID 37369946, 2023). "To test whether the expression of ALKBH1 was compromised in cancer cells, we measured the RNA levels of NSUN3 and ALKBH1." (PMID 35768510, 2022). "To directly test whether the reduction of the NSUN3-deficient metastasis-initiating population was due to the downregulation of CD36 rather than the loss of the mitochondrial RNA modifications, we stably overexpressed CD36 in NSUN3-depleted cancer cells." (PMID 35768510, 2022). "Existing basic experiments indicate that NOP1, NSUN2, NSUN3, and NSUN4 predominantly promote the majority of cancers, while NSUN5, NSUN6, and NSUN7 demonstrate context-dependent effects—promoting some cancers but inhibiting others." (PMID 41462962, 2025). "We first analyzed the mRNA expression levels of NSUN3 in pan-cancer via the TIMER database, and the result showed that NSUN3 was significantly upregulated in LIHC." (PMID 37114236, 2023). "We found that KLF3 expression was generally positively correlated with m1A, m5C, and m6A-related gene expression in pan-cancer, especially in YTHDF1, NSUN3, TET2, METTL14, YTHDC2, and FMR1." (PMID 37600783, 2023). "Both treatment strategies—inhibition of mitochondrial translation and targeting NSUN3—will, however, not target cancer cells specifically." (PMID 35768510, 2022). "Notably, the levels of expression of these genes, added to six other genes involved in mitochondria activity (TST, NSUN3, GLMP and PTCD2), were reduced following the expression of HLA-G in the RCC7 cells, consistent with mitochondrial impairment found in many types of cancer, particularly in ccRCC." (PMID 39358558, 2024).
mitochondrial disease (11 papers, 2016 to 2025). "NSUN3 is mainly responsible for specific methylation modifications of mitochondrial tRNA, and mutations in human NSUN3 are associated with mitochondrial diseases." (PMID 41462962, 2025). "–10 This study reports previously unreported candidate pathogenic variants in NSUN3 and provides detailed phenotyping and functional data confirming the role of NSUN3 in mitochondrial disease." (PMID 40465263, 2025). "Similar to the cases of other important mt-tRNA modification enzymes, mutations in the NSUN3 gene are associated with mitochondrial diseases." (PMID 36949224, 2023). "The reported human patients who have compound heterozygous mutations in the NSUN3 gene were diagnosed to develop the mitochondrial disease at several months of age13,29." (PMID 36949224, 2023). "Loss of function mutations in NSUN3, encoding the 5-methylcytosine (m5C) methyltransferase NSun3, have been linked to multisystem mitochondrial disease associated with combined oxidative phosphorylation deficiency." (PMID 32488845, 2020). "In the current study, we expand the molecular and clinical spectrum of NSUN3-related mitochondrial disease to include two novel NSUN3 missense variants and seizures." (PMID 32488845, 2020). "Mutations in the human NSUN3 gene resulting in the expression of a severely truncated protein were associated with mitochondrial dysfunction and mitochondrial disease symptoms in a patient." (PMID 29103146, 2018). "Here we have identified the mitochondrial substrate for the previously uncharacterized cytosine-5 RNA methyltransferase NSun3, found mutated in a patient with mitochondrial disease." (PMID 27356879, 2016). "Human NSUN3 mutations are associated with mitochondrial diseases." (PMID 36949224, 2023). "Disease-associated mt-tRNAMet point mutations that impair Nsun3-mediated methylation have pathological consequences, and loss of function mutations in NSUN3 are reported to cause severe multisystem mitochondrial disease associated with combined OXPHOS deficiency." (PMID 32488845, 2020). "In order to methylate C34, NSUN3 requires an intact anticodon stem loop which may explain why two mutations in this region that are associated with mitochondrial disease in humans substantially reduced C34 methylation by NSUN3 in vitro." (PMID 30311405, 2019). "This is highly suggestive of a causal link between mutations in NSUN3 and mitochondrial disease." (PMID 27356879, 2016). "The pathogenic or potentially pathogenic biallelic variants in NSUN3 disrupt mt-tRNAMet methylation and mitochondrial translation, leading to mitochondrial diseases that range from mild isolated optic atrophy to severe multi-system phenotypes, which may be accompanied by limited life expectancy." (PMID 41462962, 2025). "Loss of function mutations in NSUN3 cause multisystem mitochondrial disease associated with a combined oxidative phosphorylation (OXPHOS) deficiency, highlighting the importance of NSun3 in mitochondrial translation." (PMID 32488845, 2020). "Functional inactivation of NSUN3 as well as point mutations found in patients that occur in the vicinity of C34 on mt-tRNAMet and affect NSUN3-mediated methylation resulted in mitochondrial disease." (PMID 29103146, 2018). "To date, only NSUN2, NSUN3 and NSUN4 are known to be involved in methylation of rRNA and tRNAs in mitochondria, and mutations in mt-tRNA m5C RNA writer, NSUN3, are already recognised to cause mitochondrial disease." (PMID 39499421, 2025). "Thus, this region of the gene potentially represents a hotspot for NSUN3-related mitochondrial disease." (PMID 32488845, 2020). "Mutations in NSUN3, found in a patient with mitochondrial disease, were associated with hypomethylation and the absence of formylation of cytosine residue at position 34 of mitochondrial tRNAMet leading to impaired mitochondrial translation." (PMID 27356879, 2016).
NSUN3 also shares sentences with these, for which no sentence is quoted: glioma (3 papers); Seizure (2); acute kidney injury (1); anemia (1); anorexia nervosa (1); brain disorder (1); cardiovascular disorder (1); cervical squamous cell carcinoma (1); Encephalopathy (1); endometrial cancer (1); epilepsy (1); hypertrophic cardiomyopathy (1); hyperuricemia (1); infection (1); liver cancer (1); liver diseases (1); microcephaly (1); Mitochondrial myopathy (1); monocytic leukaemia (1); myopathy (1); non-small cell lung carcinoma (1); ovarian carcinoma (1); prostate adenocarcinoma (1); stomach cancers (1).